NAV1 (neuron navigator 1)
Description:
May be involved in neuronal migration.
Synonyms: unc53H1; KIAA1151; POMFIL3; STEERIN1; FLJ12560; FLJ14203; MGC14961; steerin-1; DKFZp781D0314
Tractability: PROTAC: ubiquitination databases record sites on it; its protein half-life has been measured.
Gene: Protein-coding gene on chromosome 1 (201,538,982 to 201,826,969, forward strand). Ensembl gene ENSG00000134369.
Subcellular location: Cytoplasm, cytoskeleton
Subcellular location (Human Protein Atlas): Microtubules
Gene Ontology:
Molecular function: protein binding
Biological process: microtubule bundle formation; nervous system development; neuron migration; neurogenesis
Cellular component: axon initial segment; microtubule cytoskeleton; cytoskeleton
Genetic constraint (gnomAD): Loss-of-function variants: 16 observed, 165.09 expected, observed/expected ratio (o/e) 0.0969, 90% interval 0.065 to 0.15. The upper end of that interval is the gene's LOEUF score, 0.15, which puts it in group 1 of 6, group 1 being the genes least tolerant of losing a copy. Missense variants: 1,679 observed, 2,444.8 expected, observed/expected ratio (o/e) 0.69, 90% interval 0.66 to 0.71. Synonymous variants: 873 observed, 990.51 expected, observed/expected ratio (o/e) 0.88, 90% interval 0.83 to 0.93.
Homologues: Orthologues: macaque NAV1 (99% identical), dog NAV1 (94% identical), guinea pig NAV1 (94% identical), rat Nav1 (93% identical), pig NAV1 (91% identical), mouse Nav1 (91% identical), chimpanzee NAV1 (87% identical), rabbit NAV1 (79% identical), tropical clawed frog nav1 (54% identical), zebrafish nav1b (50% identical), zebrafish NAV1 (42% identical), Caenorhabditis elegans unc-53 (17% identical). Paralogues in human: NAV2 (38% identical), NAV3 (37% identical).
Diseases named in the same sentence as NAV1 in open-access papers:
NAV1 is named in the same sentence as 35 diseases in open-access papers, as found by Europe PMC text mining. Sharing a sentence is not in itself a finding about the gene and the disease. The quoted sentences say what the papers report.
neuroblastoma (4 papers, 2016 to 2022). Neuroblastoma (NB) is the most common solid, extracranial childhood tumor. "Nav2 is necessary for neuritogenesis in neuron-like SH-SY5Y cells, and Nav1 is necessary for neuritogenesis in multiple systems, including neuroblastoma cells and primary hippocampal neurons." (PMID 36710926, 2022). "All three Navigators are present in neurite extensions in neurons and neuroblastoma cells, and Nav1 is especially enriched in distal ends of neurites, in growth cones, and at branch points." (PMID 36710926, 2022). "Other genes (PTK2, NAV3, NAV1, FZD1 and ATRX), expressed in neuroblastoma and involved in cell invasion and migration were mutated at frequency ranged from 4% to 2%." (PMID 27009842, 2016).
Anxiety (3 papers, 2017 to 2023). Intense feelings of nervousness, tension, or panic often arise in response to interpersonal stresses. "Annotation of the anxiety-related DMRs to genes revealed 183 genes, many of which were known stress-related genes such as NAV1, IGF2, GNAS, and CRTC1." (PMID 29225348, 2017). "Moreover, Nav1 also altered anxiety-like behavior, learning/memory, and the excitatory/inhibitory synaptic balance in hippocampal and PFC brain regions." (PMID 37853211, 2023). "While the Nav1 results also indicate that the neural circuits mediating drug reward, food reward and anxiety may have some overlap, additional research is necessary to further explore this possibility." (PMID 37853211, 2023). "We next investigated whether the Nav1 KO impacted anxiety or locomotor activity." (PMID 37853211, 2023).
epilepsy (3 papers, 2020 to 2023). A brain disorder characterized by episodes of abnormally increased neuronal discharge resulting in transient episodes of sensory or motor neurological dysfunction, or psychic dysfunction. "Outside of the arrhythmogenic mutations in NaV1.5CTD, recent findings directly link mutations in NaV1.6CTD with early infantile epilepsy [NM_001330260.2(SCN8A):c.5710C>T; p.Arg1904Cys], while early reports of NaV1.6 gain-of-function mutations have described effects on cardiac electrophysiology." (PMID 36821382, 2023). "The RT‐PCR results suggested that the mRNA levels of Btaf1, Phka1, and Nav1, which possess a strong correlation with epilepsy, were upregulated significantly." (PMID 35770064, 2022). "Together, the mRNA levels of Btaf1, Phka1, Nav1, and Magt1 were related to epilepsy." (PMID 35770064, 2022). "Moreover, to clarify the effects of AEDs on the mRNA levels of epilepsy‐related and synapse‐related proteins in Cdh5‐CreERT2;CDK5f/f mice, the mRNA levels of Btaf1, Phka1, Nav1, Bdnf, Magt1, and Grin1 were confirmed by qRT‐PCR." (PMID 35770064, 2022).
breast carcinoma (2 papers, 2022). "As to other cancer types, the NAV1 promoter hypomethylation was observed in hormone receptor positive (expressing the estrogen receptor, ER+ and/or progesterone receptor, PR+) breast cancers which seems to be consistent with our results." (PMID 35867729, 2022). "NAV1 was reported to be significantly hypomethylated in ER+/PR+ breast cancers." (PMID 35200555, 2022).
Obesity (2 papers, 2018 to 2025). Accumulation of substantial excess body fat. "Two studies agreed that genes JAZF1 and NAV1 had CpG sites significantly affected by PA relating to obesity." (PMID 40283858, 2025).
abdominal aortic aneurysm (1 paper, 2022). Enlargement and ballooning of the vessel that supplies arterial blood to the abdomen, pelvis and legs. "FGF9 and NAV1 have been implicated in the abdominal aortic aneurysm and aortic valve stenosis respectively, which may indicate the observed calcification is systemic and not isolated to the abdominal aorta." (PMID 36277789, 2022).
Alzheimer disease (1 paper, 2024). A progressive, neurodegenerative disease characterized by loss of function and death of nerve cells in several areas of the brain leading to loss of cognitive function such as memory and language. "Since NAV3 has is part of neural navigator gene family like NAV1 and NAV 2, dysregulation in NAV 3 expression can lead to abnormal neural growth and play a role is disease such as autism spectrum disorders or Alzheimer disease." (PMID 38705955, 2024).
Arthritis (1 paper, 2020). Inflammation of a joint. "One day after induction of SCW arthritis, 3 genes of this panel were upregulated: NAV1.7 (1.7-fold), ATF3 (1.8-fold), and GAP43 (1.9-fold)." (PMID 32854769, 2020).
Brugada syndrome (1 paper, 2023). A genetically heterogeneous condition characterized by complete or incomplete right bundle branch block accompanied by ST elevation in leads V1-V3. "However, the children carrying the CALM2 G114R variant displayed a phenotype commonly observed with variants in NaV1.5, i.e., Brugada Syndrome (BrS) or LQT3, where death while asleep is a common feature." (PMID 37663247, 2023).
developmental delay (1 paper, 2016). "In the Olson study, KDM5B, NAV1, and KIF21B were identified as candidate genes for developmental delay from two patients with microduplications of 1q32.1, and these genes are all common to the deleted region of our patient." (PMID 26955491, 2016).
diabetes (1 paper, 2018). "Also, for 6 of the study participants carrying the rare NaV1.7 variants, the onset of NeuP was at a similar time as the diagnosis of diabetes." (PMID 29176367, 2018).
Epileptic spasm (1 paper, 2024). A sudden flexion, extension, or mixed extension-flexion of predominantly proximal and truncal muscles that is usually more sustained than a myoclonic movement but not as sustained as a tonic seizure. "Notably, two individuals carrying KDM5B variants show epileptic spasms and/or generalized seizures, although the latter is more likely associated with a deficit in Nav1." (PMID 38575342, 2024).
glioma (1 paper, 2023). A benign or malignant brain and spinal cord tumor that arises from glial cells (astrocytes, oligodendrocytes, ependymal cells). "TTBK2, NAV1, and CTTNBP2 were considered as protective factors, while SRCIN1, TRIO, KIF18A, and SLAIN2 were risk factors for glioma." (PMID 36979179, 2023). "Moreover, TTBK2, NAV1, and CTTNBP2 were protective factors for glioma, while SRCIN1, TRIO, KIF18A, and SLAIN2 were risk factors." (PMID 36979179, 2023). "Our study found that compared with normal tissues, CTTNBP2, KIF18A, NAV1, SLAIN2, and TRIO were upregulated in glioma, while SRCIN1 and TTBK2 were downregulated." (PMID 36979179, 2023). "Compared with the normal samples, except for SLAIN2, the CTTNBP2, KIF18A, NAV1, and TRIO protein expression in glioma was elevated, while SRCIN1 and TTBK2 were decreased." (PMID 36979179, 2023).
Infertility (1 paper, 2019). "Research has also found increased embryonic lethality, decreased birthweight, and infertility in female offspring for Nav1-/- mice, suggesting an important role for Nav1 in fetal development and health." (PMID 31026301, 2019).
melanoma (1 paper, 2022). A malignant, usually aggressive tumor composed of atypical, neoplastic melanocytes. "To investigate this in more detail, we inoculated a GFP-expressing melanoma (B16F10-eGFP) cell line into Nav1.8cre::tdTomatofl/WT mice (Nav1.8 is also known as Scn10a)." (PMID 36323780, 2022). "When compared with melanoma-bearing littermate controls (Nav1.8WT::DTAfl/WT), the ablation of NaV1.8+ sensory neurons preserved the functionality of intratumoral CD8+ T cells." (PMID 36323780, 2022).
ovarian carcinoma (1 paper, 2022). A malignant neoplasm originating from the surface ovarian epithelium. "This study revealed that NAV1 expression was elevated in ovarian carcinomas (N = 110) compared to normal ovaries (N = 39) (medians of transcripts per million (TPM) equaled 7 and 4, respectively)." (PMID 35867729, 2022). "So far, no scientific reports on the NAV1 role in ovarian cancer have emerged." (PMID 35867729, 2022).
polycystic kidney disease (1 paper, 2017). A usually autosomal dominant and less frequently autosomal recessive genetic disorder characterized by the presence of numerous cysts in the kidneys leading to end-stage renal failure. "Coinciding with DTX4, NAV1 expression is also induced in a model of polycystic kidney disease and is induced in vitro by the major pro-fibrotic cytokine TGFβ, potentially linking NAV1 induction to fibrosis." (PMID 28249581, 2017).
schizophrenia (1 paper, 2022). A major psychotic disorder characterized by abnormalities in the perception or expression of reality. "While follow-up is necessary to determine the contribution of Nav1 to schizophrenia pathology, this study suggests Nav1 is involved in multiple neurodevelopmental and neuropsychiatric diseases." (PMID 36710926, 2022). "Additionally, a small but significant reduction of Nav1 mRNA was observed in the prefrontal cortex of individuals with schizophrenia." (PMID 36710926, 2022).
small-fiber neuropathy (1 paper, 2021). "Particularly, variants in the genes encoding for the NaV-1.7, −1.8, and −1.9 sodium channel subunits have been discovered in patients with small-fiber neuropathy and can lead to the development of pain." (PMID 35115925, 2021).
cancer (7 papers, 2012 to 2024). A tumor composed of atypical neoplastic, often pleomorphic cells that invade other tissues. "TIMER database was used for pan‐cancer analysis of different pain genes (Nav1, EHMT2, SP1, SLC6A4, COMT, OPRM1, OPRD1, CYP2D6, and CYP3A4)." (PMID 38352696, 2024). "MPL (proto-oncogene), NAV1 and PRRT3 are putative oncogenes implicated as candidate cancer drivers." (PMID 37166351, 2023). "However, the correlation between NAV1, TRIO, and cancer has not been well investigated." (PMID 36979179, 2023).
tumor (4 papers, 2011 to 2024). "In addition, the TP73-including model revealed Residual Tumor (RT) >2 cm as an independent factor worsening drug response, while overexpression of the NAV1 gene was associated with the lower chance of CR in the same group of patients." (PMID 35867729, 2022). "Our study revealed that the expression levels of NAV1, EHMT2, SP1, SLC6A4, OPRD1, and CYP3A4 between the normal and tumor were statistically significant." (PMID 38352696, 2024). "A recent genomic methylation analysis of 12 ER+ and 12 ER− tumors identified 5 loci that are consistently hypermethylated in one or the other tumor type (MANEAL, PER1, NAV1, FAM124B, and ST6GALNAC1)." (PMID 21364760, 2011).
NAV1 also shares sentences with these, for which no sentence is quoted: spinocerebellar ataxia (2 papers); Anosmia (1); aortic valve stenosis (1); autism spectrum disorder (1); cardiac conduction disorders (1); diabetic neuropathy (1); Epileptic encephalopathy (1); erythromelalgia (1); lung carcinoma (1); Marfan syndrome (1); neurodevelopmental disorder (1); Pan (1); scoliosis (1); serous ovarian cancer (1).